STAT3 (signal transducer and activator of transcription 3)
Diseases named in the same sentence as STAT3 in open-access papers (continued):
Sharing a sentence is not in itself a finding about the gene and the disease.
chronic mucocutaneous candidiasis (20 papers, 2011 to 2026). "Rather, the combinatorial defect of impaired STAT3 signaling downstream of these receptors explains chronic mucocutaneous candidiasis in an individual with dominant-negative STAT3 mutations." (PMID 33598806, 2021). "Chronic mucocutaneous candidiasis (CMC) patients with a dominant-negative STAT3 mutation present with a decreased number of central memory CD4+ and CD8+ lymphocytes and an increased number of naive T cells." (PMID 27703456, 2016). "Mutations in genes for IL-17 subunits or their receptors are associated with chronic mucocutaneous candidiasis (CMC), similarly to mutations affecting STAT3 and DOCK8 proteins, resulting in impaired differentiation of IL-17-secreting Th17 cells." (PMID 41481132, 2026). "In contrast to STAT3 GOF variants, inactivating STAT3 variants cause hyper-IgE syndrome which is associated with decreased Th17 cell fractions and chronic mucocutaneous candidiasis." (PMID 39359478, 2024). "Interestingly, STAT family members often cross-inhibit each other, and the hallmark clinical manifestation of STAT1 GOF is chronic mucocutaneous candidiasis (CMC), resulting from impaired Th17 differentiation due to partial STAT3 loss of function." (PMID 37275873, 2023). "STAT3–HIE, also known as Job’s syndrome, is associated with recurrent staphylococcal skin abscesses (cold abscesses), chronic mucocutaneous candidiasis (CMC), cystic pneumonia, and skeletal abnormalities." (PMID 36672710, 2023). "The possible presence of chronic mucocutaneous candidiasis (CMC) in patients with STAT3-HIES is another distinguishing feature from AD." (PMID 33717395, 2021). "Finally, people with mutations in signal transducer and activator of transcription 3 (STAT3) fail to mount a Th17 response, have significantly reduced salivary β-defensin 2 and histatins, and suffer from chronic mucocutaneous candidiasis." (PMID 28081240, 2017). "In addition, deleterious mutations in multiple direct or downstream immune effectors, notably CLEC7A, STAT3, and CARD9, have been found in human cohorts with high prevalence of chronic mucocutaneous candidiasis (CMC) and have been recapitulated and studied in mice." (PMID 21533108, 2011).
gallbladder cancer (20 papers, 2018 to 2025). "Sesamin directed the epithelial differentiation of cancer stem-like side population cells from gallbladder cancer, which is negatively associated with the NF-κB/IL-6/STAT3/Twist signaling pathway." (PMID 40303286, 2025). "Cancer-associated fibroblasts promote gallbladder cancer growth via activation of the IL6-JAK/STAT3 signal pathway." (PMID 33768003, 2021). "AG490, JAK2 inhibitor, also inhibited the proliferation and invasion of gallbladder cancer cells through inhibition of JAK2/STAT3 signaling pathway." (PMID 33917914, 2021). "The combination of STAT-3 and integrin β6 expression has been reported to have a better prognostic performance than either alone in gallbladder carcinoma." (PMID 32855767, 2020). "Additionally, it has been recently linked to gallbladder cancer metastasis through the GPRC5A, JAK2 (Janus kinase 2), STAT3 (signal transducer and activator of transcription 3), and TNS4 (tensin 4) signalling pathways." (PMID 40427604, 2025). "Moreover, exosomes from gallbladder cancer cells containing high leptin levels promote M2 macrophage polarization via STAT3 signaling and enhance gallbladder cancer cell invasion and migration." (PMID 39737074, 2024). "MOB1A furthered the survival of gallbladder cancer by inducing autophagy to reduce cellular apoptosis and activate the IL6/STAT3 signaling pathway." (PMID 37314589, 2023). "In gallbladder cancer, the expression of lncRNA-HEGBC is activated by STAT3 through STAT3 bound to the promoter of lncRNA-HEGBC." (PMID 36295083, 2022). "Leptin and its receptor LEPR promote the proliferation and metastasis of gallbladder carcinoma, which may participate in the regulation of MMPs and the VEGF family through the SOCS3/JAK2/STAT3 pathways." (PMID 33397392, 2021).
influenza (20 papers, 2013 to 2025). An acute viral infection of the respiratory tract, occurring in isolated cases, in epidemics, or in pandemics; it is caused by serologically different strains of viruses (influenzaviruses) designated A, B, and C, has a 3-day incubation period, and usually lasts for 3 to 10 days. "Same as in neutrophils, PDLIM2 expression was repressed in monocytes from influenza patients compared to those from uninfected healthy humans; and this repression was associated with ultra-activation of NF-κB and STAT3." (PMID 41000764, 2025). "Mahony and colleagues have shown that STAT3 is essential for suppressing Influenza and Vaccinia replication in the IFN-α pathway in human hepatocytes." (PMID 37784164, 2023). "Mahony and colleagues showed that STAT3 shRNA knockdown increased influenza replication while inhibiting the induction of numerous well-studied antiviral ISGs: PKR, OAS2, MxB, and ISG15." (PMID 37784164, 2023). "Our identification of STAT3 involved in H5N1-induced apoptosis opens up a new area to explore the role of STAT3 in severe influenza disease and pathogenesis." (PMID 27344974, 2016). "Similarly, IL-6 plays an important role in the cytokine storm via the JAK2/STAT3 pathway in viral and bacterial pneumonia and is a predictive marker of inflammation indicative for a poor prognosis of influenza patients." (PMID 38791439, 2024). "During post‐influenza MRSA pneumonia, baricitinib significantly reduced levels of phosphorylated STAT3." (PMID 39921246, 2025). "H5N1 and H1N1 inhibit the activation of STAT3, but H5N1 infection leads to the further activation of STAT3, which probably contributes to the pathogenesis of severe influenza disease." (PMID 32201498, 2018). "IL-6 is an important cytokine that orchestrates the acute-phase response to inflammation and actually contributes to the febrile response to influenza and other infections, via phosphorylation of STAT3 (signal transducer and activator of transcription 3)." (PMID 24116168, 2013). "A. paniculata may exert its therapeutic effects against influenza by modulating core targets such as TNF, IL‐6, AKT1, GAPDH, and STAT3." (PMID 41439108, 2025). "STAT3, a transcription factor that is part of the STAT family and involved in the interferon response, has been connected to antiviral responses, including those against influenza and vaccinia." (PMID 40143362, 2025). "A. paniculata may exert therapeutic effects against influenza by acting on core targets, such as TNF, IL‐6, AKT1, GAPDH, and STAT3." (PMID 41439108, 2025).
myelofibrosis (20 papers, 2013 to 2026). A partial or complete replacement of the bone marrow stroma by fibrous tissue. "Notably, strategies that block pathogenic cytokines via inhibition of the JAK2/STAT3 pathway have emerged as essential treatments for clinical conditions such as myelofibrosis." (PMID 39919369, 2025). "Altogether excessive MAP-kinase ERK1/2 and STAT3 activation might be linked to myelofibrosis, and contribute to cytokine-independent growth, while the PI3K appears to be the major pathway linked to proliferation." (PMID 24251790, 2013). "The FDA has approved ruxolitinib (RUX), a Janus kinase (JAK)/STAT-3 inhibitor, for the treatment of primary myelofibrosis, polycythemia vera, and vitiligo, providing clinical validation of its effectiveness in inhibiting STAT-3." (PMID 36850247, 2023). "Based on these premises, we evaluated pacritinib, a recent FDA-approved inhibitor of STAT3/JAK2 signaling for treating myelofibrosis." (PMID 31269723, 2019). "Currently, ruxolitinib, a JAK1/2-targeting agent, is widely used for myelofibrosis and polycythemia vera and showed suppression of phosphorylated STAT3 in dose dependent manner." (PMID 29340087, 2017). "Between different JAK/STAT isoforms, JAK2/STAT3 appears to be predominant for the cellular changes observed in ILDs and it is involved also in other diseases with a fibrotic phenotype (such as myelofibrosis, liver, myocardial, kidney, and skin fibrosis)." (PMID 36556466, 2022). "Past studies revealed that STAT3, VEGFA, and TNF also played an important role in the pathogenesis of myelofibrosis." (PMID 30622613, 2018). "In contrast, FDA-approved Jak/Stat3 inhibitors like ruxolitinib, which target JAK1/2 and improve survival in myelofibrosis, may offer a safer alternative." (PMID 41158754, 2026). "A number of existing drugs and natural compounds inhibit or modulate the JAK/STAT3 pathways, including resveratrol and ruxolitinib, an FDA approved drug for the treatment of myelofibrosis (MF), post-polycythemia vera myelofibrosis (PPV-MF), and post-essential thrombocythemia myelofibrosis." (PMID 29986501, 2018).
retinoblastoma (20 papers, 2014 to 2026). A malignant tumor that originates in the nuclear layer of the retina. "In addition, we showed that the action of STAT3 in retinoblastoma was linked to miR-17-92 clusters, which acted as oncogenic miRNAs, via positive feedback loop between them." (PMID 25359779, 2014). "By regulating miR-99a expression and reducing the phosphorylation of JAK1, STAT1, and STAT3, curcumin drives apoptotic cell death in retinoblastoma cells." (PMID 41020838, 2025). "Elevated H2O2 also leads to STAT3 activation which is a factor in Retinoblastoma and potential therapeutic target." (PMID 39480826, 2024). "XIST, by sponging/antagonizing miR-124, a STAT3 targeting miRNA, enhances STAT3 expression in retinoblastoma." (PMID 36922677, 2023). "The histologic examination of the tumor sample also confirmed a reduced amount of retinoblastoma tumor cells in the vitreous cavity between the lens and the retina in the STAT3 siRNA-treated group compared with the control." (PMID 38067351, 2023). "The more interesting part of the relation between STAT3 and miR-17-92 clusters in retinoblastoma cells was the positive feedback." (PMID 25359779, 2014). "Next, we investigated the roles of STAT3 activation on the expression of miR-17-92 clusters, which are highly expressed in retinoblastoma cells in our previous study and other groups' studies on miRNA expression." (PMID 25359779, 2014). "Another implication of STAT3 activation in retinoblastoma in this study was the overexpression of the well-known oncogenic miRNA family, miR-17-92 clusters." (PMID 25359779, 2014). "In this context, the treatment with STAT3 siRNA suppressed in vitro proliferation of retinoblastoma cells." (PMID 25359779, 2014). "To further investigate the roles of STAT3 in in vivo proliferation of retinoblastoma, we planned to test the therapeutic potential of STAT3 inhibition in in vivo orthotopic tumors." (PMID 25359779, 2014). "To investigate the roles of STAT3 in the proliferation of retinoblastoma cells with differential effects on the expression of representative target genes, we down-regulated the expression of STAT3 by the treatment with siRNA targeted to STAT3." (PMID 25359779, 2014). "In this study, we demonstrated that STAT3 was activated in retinoblastoma tissues from human patients." (PMID 25359779, 2014). "In summary, we found that STAT3 activation in retinoblastoma mediated various cellular events including the expression of genes related with anti-apoptotic activity and migration/invasion and the up-regulation of oncogenic miRNA, miR-17-92 clusters." (PMID 25359779, 2014). "Taken together, our results suggested that STAT3 inhibition have a therapeutic potential against retinoblastoma through the suppression of tumor proliferation." (PMID 25359779, 2014). "Real-time PCR analysis demonstrated that STAT3 siRNA down-regulated the expression of miR-17-92 clusters in retinoblastoma cells as a whole compared to scramble siRNA." (PMID 25359779, 2014). "Our data demonstrated that STAT3 activation was related with the over-expression of miR-17-92 clusters in retinoblastoma cells." (PMID 25359779, 2014). "Additionally, the JAK/STAT3 signaling pathway has been extensively studied on retinoblastoma cells and they have shown therapeutic effects by promoting cell apoptosis, via enhancing Bax and cleaved caspases 3/9 levels." (PMID 39507759, 2024). "Furthermore, STAT3/miR-17-92 clusters form a positive feedback loop that regulates proliferation of retinoblastoma." (PMID 28178652, 2017). "In conclusion, we suggest that STAT3 inhibition could be a potential therapeutic approach in retinoblastoma through the suppression of tumor proliferation." (PMID 25359779, 2014). "Interestingly, STAT3 inhibition by targeted siRNA suppresses the proliferation of retinoblastoma cells and the formation of in vivo orthotopic tumors." (PMID 25359779, 2014).
retinoblastoma (continued). "The influences of miR-17-92 clusters on retinoblastoma cells might impede the effects of STAT3 activation on these genes." (PMID 25359779, 2014). "In this context, it might be plausible for RB1-negative retinoblastoma cells to show constitutive activation of STAT3." (PMID 25359779, 2014). "Based on our data, we suggested that STAT3 inhibition could be a potential therapeutic approach in retinoblastoma beyond the focus on aberrant cell cycle machineries related with RB1 gene mutation." (PMID 25359779, 2014). "Furthermore, inhibition of STAT3 in retinoblastoma cells with targeted siRNAs resulted in impaired proliferation and down-regulation of target genes." (PMID 25359779, 2014). "In particular, the positive feedback loop of STAT3/miR-17-92 clusters might reinforce the activation of these signals in retinoblastoma." (PMID 25359779, 2014). "We speculated that these results might provide a novel therapeutic approach targeting to STAT3 in the treatment of retinoblastoma." (PMID 25359779, 2014). "This study showed that multifunctional roles of STAT3 activation in the proliferation of retinoblastoma cells as a main regulator of the expression of various target genes and miR-17-92 clusters and the therapeutic potential of STAT3 inhibition in retinoblastoma." (PMID 25359779, 2014). "We speculated that STAT3 activation in retinoblastoma cells induced proliferation of retinoblastoma cells by up-regulation of target genes with anti-apoptotic activity." (PMID 25359779, 2014). "In addition, miRNA microarray analysis and further real-time PCR experiments with STAT3 siRNA treatment show that STAT3 activation is related to the up-regulation of miR-17-92 clusters in retinoblastoma cells via positive feedback loop between them." (PMID 25359779, 2014). "Several studies have shown that STAT3 has been aberrantly expressed and activated in a variety of tumor tissues and cell lines, can participate in tumor development by inducing cell overproliferation and inhibiting apoptosis, and is aberrantly expressed in retinoblastoma." (PMID 35911143, 2022). "Although there was no definite evidence of optic nerve invasion in our cases, we could easily assume that advanced stage of our cases (all cases were graded as Va in Reese-Ellsworth Classification and E in International Classification of Retinoblastoma) might be related with STAT3 activation." (PMID 25359779, 2014). "In this study, we demonstrate that STAT3 is activated in retinoblastoma cells, Ki67-positive areas of in vivo orthotopic tumors in BALB/c nude mice, and human retinoblastoma tissues of the advanced stage." (PMID 25359779, 2014). "Our results demonstrated that STAT3 activation induced up-regulation of BCL2, BCL2L1, BIRC5, and MMP9 genes in retinoblastoma cells." (PMID 25359779, 2014). "Similarly, in retinoblastoma cells, curcumin downregulates JAK1 and STAT1/STAT3 phosphorylation while modulating miR-99a, which mechanistically leads to apoptotic cell death." (PMID 41020838, 2025). "RB1, STAT3, and CDKN2A are the most likely core targets of curcumin for retinoblastoma treatment." (PMID 35911143, 2022). "Furthermore, target genes of STAT3 including BCL2, BCL2L1, BIRC5, and MMP9 are up-regulated in retinoblastoma cells compared to other retinal constituent cells." (PMID 25359779, 2014). "In conclusion, this comprehensive network-based pharmacological analysis suggests a number of testable speculations on the potential molecular mechanisms of curcumin in the treatment of retinoblastoma and predicts RB1, STAT3, and CDKN2A as potential therapeutic targets." (PMID 35911143, 2022).